FAS (Fas cell surface death receptor)
Diseases named in the same sentence as FAS in open-access papers (continued):
Sharing a sentence is not in itself a finding about the gene and the disease.
Obesity (continued). "Inhibition of FAS in animal reduced food intake and body weight, which suggested that inhibiting intracellular FAS should be a reasonable way for treating obesity and related diseases." (PMID 22428036, 2012). "The de novo synthesis of long chain fatty acids are catalyzed by fatty acid synthase (FAS, EC 2.3.1.85), which has been considered as an anti-obesity target recently." (PMID 22428036, 2012). "Hawk tea extract could increase AMPK and ACC phosphorylation levels and downregulate SREBP1c and FAS expression to prevent obesity." (PMID 40612138, 2025). "Moreover, CYP1B1 deficiency attenuated HFD‐induced obesity and improved glucose tolerance due to the reduced expression of different adipogenic genes such as PPARγ, CD36, FAS, and SCD‐1 and increased expression of genes involved in lipolysis." (PMID 39806854, 2025). "Moreover, sex-specific differences in BAT FAS expression tend to have opposite expression patterns in response to diet-induced obesity." (PMID 38987854, 2024). "Interestingly, a previous study also showed that polyphenol-rich longan flower water extract had anti-obesity and hypolipidemic effects in rats fed a hypercaloric diet, upregulated PPARα gene expression, and decreased FAS gene expression." (PMID 36903329, 2023). "For these reasons, ketone body metabolism via AACS may play an important role in FAS-mediated lipid metabolism in BAT in high-fat diet-induced obesity." (PMID 37110178, 2023). "The intervention of 800 mg/kg/d green tea polysaccharides could up-regulate the expressions of CPT-1, down-regulate the expressions of PPARγ, SREBP-1c, FAS, and LXRα, thus significantly reducing the fat index and adipocyte area, and inhibiting mouse obesity." (PMID 35407029, 2022). "Moreover, DLW treatment decreased levels of C/EBPα and FAS, the key regulators for adipogenesis, showing anti-obesity activity due to the inhibition of adipogenesis during differentiation." (PMID 33922621, 2021). "Regarding lipid metabolism, the induction of both disorders, arthritis and obesity, alone or combined, promoted a decrease in the mRNA expression of genes involved in lipid accumulation (FAS and PPARγ) and an increase in the expression of genes related to lipolysis, such as HSL and ATGL." (PMID 34721412, 2021). "SPs have shown effects on metabolic regulation and physiological properties, such as reduction of cholesterol and triglycerides levels, improvement of lipid metabolism, anti-obesity effects, inhibition of fatty acid (FA) synthase (FAS), and ant-diabetic effects." (PMID 34445273, 2021). "In addition, proinflammatory cytokines TNF-α and IL-1β transcript expressions were also detected in the monocytes and macrophages in the mouse adipose tissue SVF, which were well correlated with the reported proinflammatory function of FAS in obesity." (PMID 33488632, 2020). "On the other hand, FAS is one of main lipogenic enzymes in obesity." (PMID 31137609, 2019). "Investigation of the manner in which SAE supplementation reduces the epididymal fat pad weight revealed that it suppresses the expression of several proteins related to adipogenesis genes, including SREBP-1, PPARγ and FAS, indicating that it exerts an anti-obesity effect by inhibiting adipogenesis." (PMID 23181109, 2012). "As a novel FAS inhibitor, α-mangostin may be applied practically in treating obesity or health care." (PMID 22428036, 2012). "Moreover, SCPE could effectively inhibit the formation of NAFLD by inhibition of LXR-α, SREBP-1c and FAS genes expression, and modulate the structural alteration of gut microbiota in obesity mice." (PMID 30736329, 2019). "Therefore, inhibiting FAS may significantly reduce weight and treat obesity under the dual mechanism." (PMID 22428036, 2012). "We observed that their expression was upregulated in the liver of diet-induced obese mice in accordance with several findings that have reported an increase in the hepatic mRNA expression of SREBP1c, FAS, and SCD1 in obesity." (PMID 40284173, 2025).
Obesity (continued). "Ant Fr also inhibited lipid accumulation by reducing the expression of PPARγ, CCAAT, C/EBPα, aP2, FAS, and LPL and enhancing the activation of the AMPK signaling pathway, demonstrating a positive impact on treating or controlling obesity." (PMID 39968092, 2025). "Hawk tea polysaccharides prevent obesity in mice by increasing the phosphorylation of AMPK and ACC, upregulating carnitine palmitoyltransferase-1 (CPT-1), and downregulating SREBP-1c and FAS expression." (PMID 40867585, 2025). "Our results showed that the PPARγ, C/EBPα, FABP4, and FAS genes were significantly downregulated in CA-treated mice, suggesting that CA may have the ability to reduce lipid accumulation and further alleviate obesity by restraining adipogenesis and lipid synthesis." (PMID 36839338, 2023). "AMPK activation inhibits downstream targets involved in obesity, such as ACC1 and FAS, which are involved in lipogenesis, and PPARγ, C/EBPα, and SREBP-1C, which are involved in adipocyte differentiation and lipid accumulation." (PMID 36839173, 2023). "Several natural polyphenols have been reported to exert anti-obesity effects by inhibiting adipocyte differentiation through the suppression of C/EBPα, PPAR-γ, FAS, SREBP-1C, and lipid metabolism (ACC-1, AMPK, FAS, and PPAR-α)." (PMID 36839173, 2023). "The authors also observed a significant reduction in FA (SREBP1, ACC, FAS) and cholesterol (HMGCR), therefore resulting in obesity prevention and improvement in metabolism of lipids." (PMID 38140305, 2023). "Considering all of this, we suggest that eGFR FAS age, FAS height, and LMR18 can be allotted as the preferred eGFR equations in children with overweight and obesity." (PMID 35211793, 2022). "In this study, down-regulation of gene expression of PPARγ, C/EBPα, SREBP-1c, aP2, FAS, LPL, and leptin in 3T3-L1 adipocytes by 18KHT01 suggested the potential effect of 18KHT01 on preventing adipogenesis, so prevent obesity." (PMID 34975503, 2021). "In HFD-induced obesity model, OT was significantly decreased the level of adipogenesis regulators including PPAR, C/EBP, FAS and aP2, while it increased the phosphorylation of perilipin and expression of ATGL." (PMID 32948162, 2020). "In the obesity model, PPARγ, C/EBPα, STREBP-1c, ACC, FABP4, FAS, and HSL were increased while PLIN was decreased in WAT." (PMID 31533255, 2019). "In the obesity model, SREBP-1c, FAS, ACC, and HMGCR were increased while adiponectin was decreased in liver." (PMID 31533255, 2019). "Our study has shown that FAS expression is significantly inhibited by EAOT administration, also suggesting that EAOTs’ anti-obesity effects are partly due to the inhibition of expression of fatty acid and TG synthesis-related proteins." (PMID 29419789, 2018). "Leptin, FAS, CEBP/α, and SREBP/1c are adipogenesis‐related genes, and obesity may induce abnormal expression of these genes." (PMID 39968210, 2025). "Likewise, deletion of some metabolic-related genes, such as FAS, Abca1, regulates HFD-induced obesity in mice via interrupting both adipocytes hypertrophy and differentiation." (PMID 40702315, 2025). "Furthermore, our investigation uncovered distinct protein expression patterns in obesity-related EC which includes elevated levels of oncogenic proteins such as TMEM205, STAT5, FAS and identified downregulation of tumor suppressor protein PIAS3." (PMID 39414985, 2024). "This unique feature imparts antioxidant protection to noncancerous tissues, making DAP compounds a potentially safe inhibitor for EV regulating oncogenic proteins (STAT3, FAS, and TMEM205), with applications in preventing obesity-mediated EC and other cancers within an obese microenvironment." (PMID 39414985, 2024). "Adipocyte-specific FAS-knockout mice promoted the conversion of white adipocytes into brown adipocytes and the activation of BAT, indicating an improvement in high-fat diet-induced obesity and insulin resistance." (PMID 37110178, 2023).
Obesity (continued). "Furthermore, changes in transcriptional factor cascades, such as increased expression of adipogenic genes (PPAR-γ, aFABP, lipogenic genes (FAS), and macrophage-specific markers (CD68, F4/80), have been reported in obesity-related studies." (PMID 36056976, 2022). "In this sense, mice lacking the lipogenic enzyme FAS in adipose tissue manifested resistance to diet-induced obesity and increased energy expenditure." (PMID 26694359, 2015). "In the VAT depot, ACC1 mRNA expression was downregulated in morbidly obese women (p = 0.013), while FAS gene expression was not significantly different in both types of obesity (p = 0.080)." (PMID 26694359, 2015). "Similarly, pear pomace soluble dietary fiber regulates obesity-related metabolic disorders by inhibiting inflammation and activating the AMPK/PPAR-α signaling pathway, which suppresses the synthesis of anabolic substances such as SREBP-1c and FAS." (PMID 40867585, 2025). "Furthermore, piceatannol, a natural stilbene compound, exerted anti-obesity effects by activating AMPK and inhibiting lipogenic proteins such as C/EBPα, PPARγ, and FAS, while altering gut microbiota composition by increasing Lactobacillus and decreasing Bacteroidetes." (PMID 41305647, 2025). "FAS plays an important role in fatty acid synthesis and inhibition of FAS expression alleviates fatty acid biosynthesis, accelerates fatty acid oxidation, consequently improves the abnormal accumulation of FFA, and thereby alleviates obesity and related lipid metabolism disease." (PMID 36231391, 2022).
Hepatic steatosis (62 papers, 2011 to 2025). Steatosis is a term used to denote lipid accumulation within hepatocytes. "Key regulatory proteins identified in association with the increased hepatic steatosis included underlying mechanisms associated with lipid synthesis including ChREBP, FAS, SREBP1c, and their target genes." (PMID 39896731, 2025). "In addition, CD47ASO treatment reduced hepatic steatosis as demonstrated by reduced liver Oil Red O staining and liver triglyceride measurement, which was associated with reduced expression of lipid synthesis genes including FAS, ACC and SCD1." (PMID 36797364, 2023). "In patients with fatty liver disease, cellular FAS expression correlated with the degree of steatosis." (PMID 41321651, 2025). "Water extracts of shepherd’s purse show potential in improving lipid metabolism disorders and hepatic steatosis in fructose-fed mice, which effect is achieved through the modulation of the FAS/ACC pathway." (PMID 39599706, 2024). "Consistently, the knockout of PPARγ in db/db mice noticeably mitigated hepatic steatosis by downregulating the expression of genes such as FAS, SCD1, and ACC." (PMID 38441531, 2024). "As a result, inhibition of AMPK phosphorylation by chronic alcohol consumption increases SREBP-1, PPAR-γ, and FAS expression, contributing to the development of hepatic steatosis, so AMPK can be considered a focus for the treatment of AFLD." (PMID 38542468, 2024). "During the process of HFD causing hepatic steatosis, the two rate-limiting enzymes for lipogenesis, ACC and FAS showed sensitive reactions and significant increases in response to HFD, similar to our previous studies." (PMID 35457022, 2022). "In mice fed with a choline-deficient high-fat diet, which induces NASH, branched-chain amino acids supplementation alleviated hepatic steatosis and liver injury associated with NASH by suppressing the expression of FAS gene and its protein levels." (PMID 35055797, 2022). "Our results found T090 can cause liver steatosis at a concentration of 2 mg/kg/d and increase the key lipogenic factors including SREBP-1c, FAS, and SCD-1." (PMID 35959429, 2022). "Noteworthy, the liver specific FAS knockout aggravates hepatic steatosis, thus suggesting that FAS has a prominent protective effect in the liver." (PMID 32772323, 2021). "OGA-treated db/db mice display a decrease in FAS expression and escape hepatic steatosis in correlation with a downregulation of the O-GlcNAcylation of ChREBP." (PMID 26835421, 2016). "As documented in two lines of mouse studies, palmitoleate inhibits hepatic FAS expression, and is thought to decrease hepatic steatosis." (PMID 22768070, 2012). "Excessive iodine could induce oxidative stress and disturb thyroid hormone metabolism by upregulating mRNA expression for SREBP-1c and FAS (fatty acid synthase) in the liver, which plays a pivotal role in hepatic steatosis." (PMID 40431366, 2025). "BCAAs might decrease the serum ALT levels, as well as alleviate hepatic steatosis and liver injury, by suppressing FAS gene expression, protein levels, and oxidative stress." (PMID 39064737, 2024). "This lncRNA negatively regulates endogenous SREBP-1c and FAS; and it can suppress TG accumulation and may be a protective molecule against hepatic steatosis." (PMID 36979720, 2023). "AAs could alleviate hepatic steatosis and liver injury associated with NASH by suppressing FAS gene expression and protein levels." (PMID 34200685, 2021). "Also, high-fat diet-induced hepatic steatosis in obese mice were associated with inhibited PPARα activity and increased expressions of SREBP-1c, as well as its target genes, FAS and SCD-1." (PMID 30398974, 2018). "Interestingly at that time, 30% of the obese rats showed signs of hepatic steatosis and exhibited increased hepatic FAS and ACC mRNA levels." (PMID 25822172, 2015).
Hepatic steatosis (continued). "Given that food restriction has a powerful effect on reducing hepatic steatosis, the decrease in liver FAS expression in palmitoleate-supplemented KKAy mice could be attributed solely to reduction of food intake associated with palmitoleate dosing." (PMID 22768070, 2012). "Thus, the effects of PCSK9 in olanzapine-related hepatic steatosis may be mediated via the upregulation of FAS and SCD1." (PMID 35379885, 2022). "Despite palmitoleate inducing hepatic steatosis, this FA may dissociate the liver inflammatory response from hepatic steatosis, and promote insulin-sensitization and its pro-lipogenic effect, by enhancing hepatic FAS expression due to higher expression of SREBP-1c." (PMID 29065507, 2017). "Expression of hepatic genes involved in cholesterol metabolism (SREBP2, HMGCR, and ApoB) and lipogenesis (SREPB1c, SCD-1, FAS, and Acacα) was suppressed in the experimental group, and may have favorably affected hyperlipidemia and hepatic steatosis induced by the high-fat diet." (PMID 22027268, 2011). "Recombinant IL-22 inhibited the hepatic expression of several lipogenic genes, including that of fatty acid synthase (FAS) in HepG2 cell line and HFD-induced NAFLD mice, which led to the reduction of hepatic steatosis." (PMID 40794228, 2025). "Cichoric acid plays an important role in reducing hepatic steatosis, as it reduces the expression of lipogenic actors, such as SREBP-1c, DGAT1, FAS, and SCD-1, and also of inflammatory factors such as IL-6, IL-1b, NF-κB, and TNF-α." (PMID 39458995, 2024). "Overexpression of ATF4 triggers liver steatosis in zebrafish, while silencing of ATF4 leads to a reduction of lipogenic genes, including PPAR-γ, SREBP-1, ACC and FAS, in the liver and adipose tissue of mice." (PMID 38216941, 2024). "The upregulation of SREBP-1c, along with its downstream genes including FAS and ACC, as well as the downregulation of PPAR-α, are recognized as the interfering factors contributing to the development of hepatic steatosis." (PMID 38004120, 2023). "Previous evidence typically demonstrated that FAS and SCD1, PPARγ in an inverse correlation between fatty liver and fibrosis." (PMID 33673073, 2021). "Overexpression of intramuscular Irisin reduces hepatic steatosis by inhibiting lipogenic factors, such as SREBP-1 and FAS, in hepatocytes." (PMID 33182720, 2020). "In the present study, in rats fed the HFS diet we observed a marked accumulation of lipid droplets in the liver indicating hepatic steatosis and a greater expression of SREBP-1 and FAS in the liver, compared with the control group." (PMID 28680065, 2017). "At the molecular level, losartan only significantly decreased FAT/CD36 and FAS mRNA together with UCP2 mRNA, but these effects appear insufficient to impact hepatic steatosis or ATP content respectively." (PMID 28231800, 2017). "In our study, TO-treated db/db mice exhibited more extensive hepatic steatosis than the control group, most likely due to SREBP-1c-mediated up-regulation of lipogenetic genes, such as SCD-1 and FAS, etc." (PMID 25909991, 2015). "Additionally, by inhibiting the FAS and Nrf2 pathways, it decreases the expression of CD36, SREBP1c, and the small heterodimer partner (SHP), which decreases hepatic steatosis." (PMID 39061866, 2024). "Moreover, other studies administrating chemical activators of SIRT1, resveratrol and SRT1720, or the NAD+ precursor nicotinamide riboside, reduced SREBP1c, FAS, SCD1 gene and protein expression in the liver of mice/rats with HFD-induced hepatic steatosis." (PMID 39264516, 2024). "Overexpression of FAS may induce an increase in the development of fatty liver and PPAR-α agonism could reduce the elevation of FAS mRNA expression." (PMID 35883883, 2022). "Finally, P2rx7−/− mice developed a hepatic steatosis characterized by a reduction of Acaca, Acacb, Fasn and Acox1 mRNA expression, as well as for ACC and FAS protein expression." (PMID 29018292, 2017).
Hepatic steatosis (continued). "This reduced hepatic steatosis could be attributed to a reduction in de novo lipogenesis promoted by chrysin, as gene analysis showed that the marked increase in FAS expression prompted by a HFD was no longer present upon chrysin treatment." (PMID 39860248, 2025). "In HFD-fed rats and FFA-induced HepG2 cells, except for the alleviation effect of KTZG on lipid accumulation and hepatic steatosis, our results showed that KTZG could regulate the expression of these lipid-related genes, upregulating PPAR-γ and Sirt and downregulating FAS and SREBP-1." (PMID 32884949, 2020). "Hepatic steatosis might be mediated partly by regulating SREBP-1c, a key transcription factor of lipogenic genes in fatty acid synthesis and TGs, including ACC, SCD, and FAS." (PMID 29295591, 2017). "However, FAS expression decreased after EtOH+Chol feeding, indicating that hepatic steatosis was not due to increased de novo fatty acid synthesis." (PMID 27676640, 2016). "This could be attributed to the protective role of MSCs-Exo+EVOO against hepatic steatosis via promoting lipid oxidation related factors, PPARα, CPT-1, and ACOX, involved in fatty acid oxidation and suppressing synthesis of fatty acid via controlling PPARα, CPT-1A, SREBP-1, and FAS expression." (PMID 41144456, 2025). "We observed that FAS mRNA expression is decreased in HFD-fed rats compared with chow-fed rats, indicating that de novo lipogenesis does not contribute significantly to HFD-induced hepatic steatosis." (PMID 33746771, 2021).